RYR1 (ryanodine receptor 1)
Diseases named in the same sentence as RYR1 in open-access papers (continued):
Sharing a sentence is not in itself a finding about the gene and the disease.
thyroid tumor (1 paper, 2022). A benign or malignant neoplasm affecting the thyroid gland. "We aimed to evaluate the common mutated genes (JMJD1C, MALAT1, MUC16, PDZD2, PKHD1, RYR1, SLA and TTN) between thyroid tumor and normal samples." (PMID 35996174, 2022).
TTR amyloidosis (1 paper, 2025). "According to the ACMG guidelines on secondary findings, RYR1 and TTR are associated with malignant hyperthermia and hereditary TTR amyloidosis, respectively." (PMID 41296379, 2025).
tubular aggregate myopathy (1 paper, 2022). Tubular aggregate myopathy is a disorder that affects the skeletal muscles. "Identification of RYR1 mutations uncovers the fourth gene causative of tubular aggregate myopathy." (PMID 35666680, 2022).
Ventricular arrhythmia (1 paper, 2025). "We did not observe a significant association between specific RYR1 SNPs and ventricular arrhythmias in the UIC-HF cohort." (PMID 40060969, 2025).
myopathies (193 papers, 2007 to 2026). "Mutations in RyR1 are linked to severe myopathies, including malignant hyperthermia (MH) and central core disease (CCD), both of which are associated with dysfunctional calcium homeostasis." (PMID 41253812, 2025). "RyR1-related myopathies (RyR1-RMs) include a wide range of genetic disorders that result from mutations in the RYR1 gene." (PMID 40243436, 2025). "Previously, several studies identified leaky RyR1 channels as an underlying cause of impaired Ca2+ release and thereby muscle weakness in myopathies." (PMID 40183240, 2025). "Severe congenital RYR1-associated myopathy, a central core myopathy, results from mutations in the gene encoding the skeletal muscle RYR1 channel." (PMID 40268053, 2025). "RYR1 variants can lead to defective calcium release in malignant hyperthermia, myopathies, and neuromuscular disorders." (PMID 41440556, 2025). "We identified a rare in-frame duplication in exon 91 of the RYR1 gene associated with variability in the phenotype of MH susceptibility, characterized by dysmorphisms and mild myopathy." (PMID 41300704, 2025). "To get a better idea of the clinical spectrum associated with autosomal recessive RYR1-related myopathy, we included data of five additional patients from our center detected via exome sequencing over recent years." (PMID 39409197, 2024). "We and others have demonstrated that myopathy-associated variants in CCDC78 lead to the mislocalization of RyR1, a calcium channel protein that localizes to the triad." (PMID 38732148, 2024). "A panel analysis for myopathies including 128 genes was performed at the age of two months which revealed a known pathogenic splice variant in the RYR1 gene in a heterozygous state: c.14364+1G>A (NM_000540.3)." (PMID 39409197, 2024). "We report the first correction from prime editing a mutation in the RYR1 gene, paving the way to gene therapies for RYR1-related myopathies." (PMID 38201236, 2023). "Families susceptible to MH and having the non-myopathy phenotype harbor one of nearly 230 single-point RyR1 mutations, which are responsible for the defective RyR1 functioning, manifested by channel overactivity to volatile anesthetics." (PMID 36982484, 2023). "Compound heterozygous mice with one TM allele and one frameshift (null) allele express a markedly lower level of RyR1 channels (~ 80% reduction) and exhibit an even more severe (post-natal lethal) myopathy." (PMID 37670077, 2023). "In some new cases of RyR1-related myopathies, pathologic SR Ca2+ leak was shown to be associated with low levels of the regulatory protein FKBP12 (calstabin) bound to the RyR126." (PMID 37670077, 2023). "RyR1-RM is, in some patients, a progressive myopathy that results in loss of muscle function over time." (PMID 36647824, 2023). "The mutation in mice was of additional interest because the majority of RYR1 myopathies so far examined in animal models explore the effects of autosomal dominant RYR1 mutations." (PMID 38203604, 2023). "Here we report the first identification of mutations in RYR1 in two unrelated patients with clinical symptoms of a mild myopathy and the presence of tubular aggregates as the sole pathological abnormality on muscle biopsy." (PMID 35666680, 2022). "We found several mutations in RyR1 transmembrane region that had been previously associated to core myopathies, i.e. p.Arg4861His, p.Thr4882Met, p.His4887Tyr, p.Ala4894Pro, p.Gly4897Asp, p.Ile4898Thr, p.Gly4899Arg, p.Ala4940Thr, p.Pro4973Leu and p.Phe4976Leu." (PMID 35428369, 2022). "Accordingly, these data suggest that RYR1 should be considered for genetic analysis in a myopathy with TA where STIM1, ORAI1 and CASQ1 mutations have been excluded." (PMID 35666680, 2022). "Our study aims to describe the RYR1 variant landscape in a Singaporean cohort unselected for RYR1-associated myopathies and MH." (PMID 35361824, 2022).
myopathies (continued). "Accordingly, to gain insights into the pathogenesis and pathological process of malignant hyperthermia, suitable biomarkers for the diagnosis and treatment of RYR1 mutation-associated myopathies should be found." (PMID 35692882, 2022). "Most of the genetic studies done on RYR1 mutations were performed on patients diagnosed with MH and other myopathies, and this is useful in identifying pathogenic variants." (PMID 35361824, 2022). "RYR1 functions as a regulator of inner cell Ca2+ flow, the dysfunctions of this factor have been implicated in heart conditions, myopathies and neurodegenerative disease." (PMID 36026497, 2022). "Compared with the normal group, the group of RYR1 mutation-associated myopathies was differentially expressed (|logFC| > 1, p.adj < 0.05)." (PMID 35692882, 2022). "Cytoscape identification of hub genes correlated with RYR1 mutation-associated myopathies was used to determine the core genes associated with RYR1 mutation to explore the potential pathogenesis of RYR1 mutation-associated myopathies." (PMID 35692882, 2022). "TNNT3 is recognized as a novel effective biomarker for diagnosing RYR1 mutation-associated myopathies." (PMID 35692882, 2022). "Mice with the corresponding I4895T mutation in Ryr1 present mild myopathy when the mutation is heterozygous while I4895T homozygous is perinatal-lethal." (PMID 36450915, 2022). "The mRNA expression profiles of RYR1 mutation-associated myopathies and normal skeletal muscle tissues were obtained from GEO database to determine DEGs correlated with RYR1 mutation-associated myopathies." (PMID 35692882, 2022). "PCA was performed to determine differences between RYR1 mutation-associated myopathies and control samples." (PMID 35692882, 2022). "Skeletal muscle tissue microarray datasets of RYR1 mutation-associated myopathies or healthy persons were built in accordance with the gene expression synthesis (GEO) database." (PMID 35692882, 2022). "Identification of mutations in RYR1 represents an unexpected finding, since myopathies caused by RYR1 mutations are usually associated with the presence of cores of different morphologies in muscle biopsy of these patients." (PMID 35666680, 2022). "Mutations in the recessive central core and multi-minicore myopathies are more extensively distributed along the RYR1 sequence, whereas most heterozygous dominant mutations in central core myopathy are mapped to the C-terminal domain." (PMID 36292611, 2022). "At least one RYR1 mutation was identified in 69 core myopathy patients and these have been further studied." (PMID 35428369, 2022). "Core myopathy and NM were the most frequent pathologies in our cohort, and RYR1 was the most common associated gene, similar to previous reports but with varied rates between studies." (PMID 35081925, 2022). "Here, we report on the identification of causative dominant RYR1 variants in two patients with a history of myopathy characterized by the presence of tubular aggregates in muscle biopsy and negative for mutations in STIM11, ORAI1 and CASQ1." (PMID 35666680, 2022). "Many of the RYR1-associated myopathies are linked to MH-susceptibility, and it is estimated that MH-susceptibility and myopathy co-occur in at least 30% of individuals with RYR1 pathogenic variants." (PMID 35361824, 2022). "Accordingly, finding suitable biomarkers with diagnostic potential is of great significance for understanding the pathogenesis of RYR1 mutation-associated myopathies and accurate diagnosis as soon as possible." (PMID 35692882, 2022). "This study provides a reference for the diagnosis and therapeutic targets of RYR1 mutation-associated myopathies and helps anesthesiologists choose a reasonable anesthesia mode and prepare for malignant hyperthermia in patients." (PMID 35692882, 2022). "Second, most of our data were obtained from specimens of RYR1 mutation-associated myopathy patients and normal healthy subjects through the biological information assay." (PMID 35692882, 2022).
myopathies (continued). "We identified 170 DEGs among 11 muscle biopsy samples of healthy subjects and 17 muscle biopsy samples of RYR1 mutation-associated myopathy patients in the dataset." (PMID 35692882, 2022). "The ROC curve analysis showed that MYH1, ATP2A1, TNNT3, and MYLPF showed good diagnostic performance for RYR1 mutation-associated myopathies." (PMID 35692882, 2022). "This has provided further evidence that mutations in one gene, as in RYR1-related disorders, result in several different myopathies characterized by a spectrum of clinical and histopathological phenotypes." (PMID 35980353, 2022). "We screened a cohort of 153 patients carrying an histopathological diagnosis of core myopathy (cores and minicores) for RYR1 mutation." (PMID 35428369, 2022). "In contrast to early-onset RYR1-related myopathies that affect the medial and anterior thigh compartment, few cases of late-onset axial myopathy have been associated with RYR1 mutations." (PMID 35980353, 2022). "MYH1 (AUC: 0.856) achieved the maximum diagnostic value in RYR1 mutation-associated myopathies samples, and the diagnostic values of other genes included the following: TNNT3 (AUC: 0.840), MYLPF (AUC: 0.786), and ATP2A1 (AUC: 0.765)." (PMID 35692882, 2022). "The results of this study contribute to the explanation of the pathogenesis of RYR1 mutation-associated myopathies and are beneficial to find out the molecular mechanism of the pathological process." (PMID 35692882, 2022). "Another RyR1 variant Tyr522Ser causes continuous Ca2+ leakage, high levels of reactive nitrogen and oxygen species, and the development of a myopathy characterized by decreased muscle performance and mitochondrial damage." (PMID 35001666, 2022). "Abnormal expression of MYH1 is closely related to muscle diseases, so MYH1 is of great significance in explaining the pathogenesis, development, and diagnosis of RYR1 mutation-associated myopathies." (PMID 35692882, 2022). "The NTR hosts numerous mutations linked to skeletal (RyR1) and cardiac (RyR2) myopathies, highlighting its potential as a therapeutic target." (PMID 34793835, 2022). "The present study extends these observations at the atomic level by focusing on structure/function studies of the ATP and Ca2+ binding sites and disease causing mutations that affect these sites in patients with RyR1-myopathy." (PMID 34809703, 2021). "It is worth noting here that the enhanced Caf-induced skeletal muscle contraction is a hallmark for diagnosis for MH, a RyR1 mutation–associated myopathy." (PMID 34352272, 2021). "In recessive RYR1-related myopathies, mutations are widespread across the entire RYR1 gene, usually identified as a combination of a null mutation and a missense mutation or two missense mutations, with the variable clinical severity." (PMID 34208776, 2021). "Aberrant Ca2+ leak through ryanodine receptor 1 (RyR1) on the sarcoplasmic reticulum (SR) membrane can lead to heatstroke and malignant hyperthermia (MH) susceptibility, as well as severe myopathy." (PMID 34705503, 2021). "The patient in the database with this mutation also had a second mutation, A538T; however, this mutation is located in the NTD of RyR1, which is far from ligand binding sites and myopathy hotspots." (PMID 34809703, 2021). "RYR1-related myopathies are a group of skeletal muscle disorders caused by mutations in the ryanodine receptor gene, RYR1." (PMID 34205993, 2021). "An unusual adult‐onset, mild calf‐predominant myopathy in combination with well‐defined cores and multicore‐like unevenness of stain was reported due to RYR1 mutations." (PMID 34170073, 2021). "Recessive mutations in RYR1 cause different albeit overlapping myopathies including multi-minicore disease (MmD), congenital fiber type disproportion, or CNM." (PMID 34768808, 2021).
myopathies (continued). "Core myopathies are often caused by autosomal dominant or recessive mutations in the RYR1 gene, encoding the skeletal muscle ryanodine receptor RYR1, a redox-sensitive Ca2+ channel of the sarcoplasmic reticulum (SR)." (PMID 34066362, 2021). "Numerous mutations in the RYR1 gene encoding the ryanodine receptor result in genetic diseases among which two core myopathies: Central Core Disease (CCD, OMIM#117000) and Multiminicore disease (MmD, OMIM#255320)." (PMID 33176865, 2020). "MH is a myopathy typically caused by any one of numerous, typically-dominant, missense variants in RyR1, where exposure to inhalational anaesthetics results in a severe, potentially fatal, reaction due to uncontrolled opening of the Ca2+ channel." (PMID 32174957, 2020). "Congenital myopathies are mostly disorders of EC coupling and altered calcium handling, and numerous mutations in the RyR1 gene have been identified as the cause of myopathy." (PMID 32222817, 2020). "Nuanced terminology is evident within the literature (including RYR1-related, RYR1-associated, RYR1-related congenital, RYR1-congenital) myopathies." (PMID 33190635, 2020). "Two mutations in human RyR1 SPRY1 have previously been linked to myopathies: D708N has been linked to multi-minicore disease and atypical periodic paralysis, while N759D is associated with central core disease." (PMID 32899693, 2020). "Congenital muscle diseases in humans can result from mutations in at least 20 genes, but mutations in the gene for ryanodine receptor 1 (RyR1) are the most common cause of such myopathies." (PMID 32372758, 2020). "The most prevalent phenotype associated with the RYR1 mutations identified in this work was central core myopathy in both dominant and recessive forms of disease inheritance." (PMID 32403337, 2020). "Mutations in the gene that codes for RYR1 in humans cause a group of rare diseases called RYR1-related myopathies." (PMID 32223895, 2020). "Conversely, the C-terminal mutation in Ryr1I4898T/+ mice causes uncoupled RYR1 functionality that results in a severe core myopathy." (PMID 31874912, 2019). "There are currently two knock-in lines with N-terminal Ryr1 mutations resulting in a core myopathy with MHS." (PMID 31874912, 2019). "RYR1 mutations are the major cause of core myopathies and, as such, have been the most widely studied core myopathy mutation in animal models." (PMID 31874912, 2019). "In recent years, autosomal recessively inherited myopathies associated with sequence variants (SVs) in the RYR1 gene and with a broad phenotypic and histopathological spectrum have been reported." (PMID 31165076, 2019). "Concordantly, approximately 50% of patients with multi-minicore myopathies are found with recessive mutations in RYR1 and SEPN1 which are also genes related to Ca+2 homeostasis." (PMID 30770808, 2019). "This reinforces the importance of detecting RYR1 variants, even in those with only mild myopathy-related symptoms, as such individuals can still be at risk." (PMID 30155738, 2018). "Accordingly, a central question of the pathophysiology of RyR1-related myopathies is the identification of pathways linking RyR1 mutations to mitochondrial dysfunction and loss." (PMID 29701772, 2018). "We suggest that cases compound heterozygous for RYR1 nonsense and missense mutations are more likely to have a concomitant early-onset myopathy." (PMID 29298851, 2018). "Diagnostic testing in the same commercial laboratory excluded the presence of deletions and duplications in genes causative of distal myopathies and in RYR1 by comparative genomic hybridization (CGH)." (PMID 29178655, 2017). "Defining the mechanisms underlying the pathology of RyR1 myopathies is a critical first step towards developing interventions." (PMID 28337975, 2017). "Causative mutations in the gene (RYR1), which encode the major sarcoplasmic reticulum calcium release channel of skeletal muscle (RyR1), have been found in several myopathy subtypes." (PMID 27855725, 2016).